IDH1 (isocitrate dehydrogenase (NADP(+)) 1)
Diseases named in the same sentence as IDH1 in open-access papers (continued):
Sharing a sentence is not in itself a finding about the gene and the disease.
glioblastoma (continued). "Transduction with mutant IDH1 led to a reproducible and significant radio-sensitization in the glioblastoma cell line U87-MG and astrocytes SVGp12 (p < 0.001), while the survival curves of vector control and IDH-mutated patient derived cell line HT7606 did not systematically differ." (PMID 31888244, 2019). "Therefore, we will try to create the glioblastoma with IDH1 knockout stable cells by CRISPR strategy and further knock-in several mutant forms of IDH1, including R132H, R132Q, and S92A, through virus infection." (PMID 31450822, 2019). "Additionally, investigators recently found that patients with isocitrate dehydrogenase 1 (IDH1)-mutant glioblastoma had a better prognosis than IDH1 wild type glioblastoma." (PMID 30828330, 2019). "Moreover, the IDH1-mutant cells had overall lower protein levels of NAMPT compared to IDH1-wildtype glioblastoma cells." (PMID 31888244, 2019). "In glioblastoma, its clinical application could support IDH1 in achieving a prognostic stratification." (PMID 31434323, 2019). "It was found that the mutations of IDH1/2 could promote the formation of the tumor microenvironment by increasing the expression of VEGF and make it suitable for glioblastoma stem cell development." (PMID 31263678, 2019). "IDH1 mutation but not 2-HG alone led to decreased cell growth in glioblastoma cells as well as astrocytes in vitro." (PMID 31888244, 2019). "One of the glioblastoma subtypes, proneural subtype, has features of high expression of platelet derived growth factor receptor alpha (PDGFRA) or isocitrate dehydrogenase 1 (IDH1) gene mutation." (PMID 30709063, 2019). "A very interesting study came from the comprehensive analysis of mutation in glioblastoma multiforme (GBM) by the Hopkins team in 2008, which led to the discovery of a recurrent mutation R132H in isocitrate dehydrogenase 1 (IDH1) and the mutation was shown to be associated with better survival." (PMID 31497535, 2019). "With a long course of slowly progressing, this was a rare case of secondary glioblastoma with the absence of isocitrate dehydrogenase 1 (IDH1) gene mutation." (PMID 31555204, 2019). "Finally, we investigated the relation of the identified CD44+/CD133+/ITGA6+/CD36+ signature to the four glioblastoma molecular subtypes (mesenchymal, neural, proneural, and classical) as well as the isocitrate dehydrogenase 1 (IDH1) status." (PMID 30467961, 2019). "One study searched for genetic alterations in glioblastomas occurring with or without IDH1 mutations (typical for secondary and primary glioblastoma) using data from The Cancer Genome Atlas (TCGA) and identified 25 genes, of which 21 were located at 7q31–34." (PMID 31221203, 2019). "Furthermore, it has been shown that many histologically identified as WHO grade II and especially WHO grade III IDH1-wildtype diffuse gliomas in adults display molecular characteristics and behaviors of a glioblastoma." (PMID 31242696, 2019). "Furthermore, the glioblastoma cell lines lack the IDH1 R132 mutant form for the experiments predicted." (PMID 31450822, 2019). "Molecular and immunohistochemical signatures classified our series as IDH1-wild type glioblastomas." (PMID 29805974, 2018). "In this study, having access to IDH1 wild-type glioblastoma of patients with exceptionally long recurrence free survival (RFS), we decided to compare their mutational and gene expression profile to groups of IDH1 wild-type glioblastoma of patients with shorter RFS, by using NGS technology." (PMID 29844869, 2018). "Of note, SLUG (median test: p=0.0098) and TWIST (median test: p=0.0315) expression were significantly higher in IDH-1-wildtype as compared to IDH-1-mutant (R132H) glioblastomas, most probably related to the a priori more prominent neoangiogenesis in primary glioblastoma (data not shown)." (PMID 29844871, 2018).
glioblastoma (continued). "This has been attributed to mutations in the IDH1 gene, which are exclusively linked with the proneural phenotype and grade II/III of astrocytic and oligodendroglial tumors (72–100%) along with secondary glioblastomas (85%)." (PMID 28316990, 2017). "The results implied that CYTOR and MIAT may be associated with amplification of PDGFRA and IDH1 mutations, HAR1A may be related with neuron markers in glioblastomas." (PMID 29108264, 2017). "In glioblastoma, ZEB1 labeling index is higher in tumors with EGFR amplification or IDH1 mutation." (PMID 28945795, 2017). "IDH1 wild type and TERT mutation tumors are commonly seen in glioblastoma." (PMID 28915860, 2017). "While IDH1/2 mutations occur in diffuse astrocytoma, oligodendroglial tumors and secondary glioblastoma they were absent in our PXA and gcGBM samples, which differentiates PXA as well as gcGBM from diffuse astrocytoma." (PMID 27253461, 2016). "Primary glioblastomas (originating de novo) are wild type for IDH1 and IDH2." (PMID 27586084, 2016). "However, the most recent WHO classification of brain tumors has reserved the diagnosis “glioblastomas NOS” for tumors for which full IDH1/2 evaluation cannot be performed." (PMID 27626492, 2016). "Since 2008, with the discovery of recurrent mutations in the IDH1 coding gene by the Vogelstein group analyzing the DNA sequence of the glioblastoma genome, substantial progress has been made to understand how such genetic modification leads IDH1 to play a role in the tumorigenesis." (PMID 26858939, 2016). "Notably, with the exception of three BRAF mutated glioblastomas concurrently harboring TERTp mutation, BRAF, H3F3A, IDH1, TERTp mutations and EGFR amplification were mutually exclusive." (PMID 26452024, 2016). "One of the exciting observations is the presence of IDH1 mutation in the vast majority of secondary glioblastoma, while it is almost absent in primary glioblastoma." (PMID 26858939, 2016). "They show that GBM with IDH1 mutation diagnosed as primary had clinical and genetic profiles similar to those of secondary glioblastomas, suggesting that they may have rapidly progressed from a less malignant precursor lesion that escaped clinical diagnosis and were thus misclassified as primary." (PMID 26143636, 2015). "Moreover, shRNA-directed knockdown of IDH1 led to strong downregulation of BCAT1 expression in glioblastoma cell lines." (PMID 26372729, 2015). "IDH1 mutations occurs in a vast majority of diffuse astrocytomas, oligodendrogliomas, and mixed oligoastrocytomas of WHO grades II and III and an earlier important findings in a fraction of secondary and primary glioblastomas." (PMID 27275230, 2015). "Among the 13 patients with primary glioblastoma, none had an isocitrate dehydrogenase IDH1 or IDH2 mutation, and 3 patients (3/13; 23 %) showed radiographic responses or SD ≥6 cycles." (PMID 25529192, 2015). "Somatic mutations in IDH1 and IDH2 are described in glioblastomas (GBMs)." (PMID 26948489, 2015). "Aside from three primary central nervous system (CNS) tumors (2 oligodendrogliomas and 1 glioblastoma) with a single genetic lesion (IDH1 R132H mutation), no two patients within a given histology or organ-based diagnosis were molecularly identical." (PMID 26418953, 2015). "Recent genome-wide mutational analyses have demonstrated the presence of isocitrate dehydrogenase 1 (IDH1) mutations in more than 70% of WHO grade II and III astrocytomas, oligodendrogliomas, and secondary glioblastomas (GBMs), whereas fewer than 5% of primary GBMs harbor this mutation." (PMID 26115094, 2015). "The positivity of IDH1 in primary glioblastomas in different studies." (PMID 27275230, 2015).
glioblastoma (continued). "Interestingly, many low grade glioblastomas possess a defect in the cytosolic isocitrate dehydrogenase (IDH1) which functions in converting isocitrate to α-ketoglutarate concomitant with the production of NADPH." (PMID 26070193, 2015). "However, in contrast to majority of the previous studies, the present study clarified a relatively higher degree of expression of the IDH1 in primary glioblastoma (17.64%)." (PMID 27275230, 2015). "To test this hypothesis, we treated isogenic pairs of murine Ink4a-Arf−/− EGFRvIII glioblastoma lines expressing either IDH1-R132H or wild type IDH1 with the EGFR inhibitor, Gefitinib." (PMID 25277177, 2014). "To test this hypothesis, we exogenously expressed IDH1-R132H to induce a G-CIMP+ state in the human U87MG glioblastoma line as well as an Ink4a-Arf−/− genetically engineered murine model (GEMM) derived glioblastoma line." (PMID 25277177, 2014). "These eligibility criteria would most likely exclude older patients who generally have primary glioblastomas without IDH1/2 mutations." (PMID 24952577, 2014). "In addition, up-regulation of PC has been shown to enable glutamine-independent growth of wild-type IDH1 glioblastoma cells, indicating that PC can serve as a metabolic alternative to glutamine." (PMID 25243911, 2014). "Similarly, we detected heterogeneity of PDGFRA amplification within BI06, an IDH1-mutant glioblastoma." (PMID 25608559, 2014). "In contrast, those primary and more aggressive glioblastomas are generally negative for IDH1 mutation, and it seems that IDH-mutation is related to prognosis." (PMID 25482099, 2014). "IDH1 mutant glioblastomas have been shown to differ in their epigenetic and genomic presentation." (PMID 23451042, 2013). "Differences in demographics and tumour location between IDH1 mutant and wild-type glioblastomas further suggest different aetiologies of what may be seen to be two distinct disease entities." (PMID 23451042, 2013). "The concept of sequential molecular evolution of the IDH1 mutant glioblastoma has been conceived." (PMID 24202337, 2013). "We sought to address this by carefully assessing the morphological characteristics of both the tumour cells and the associated vasculature, relating these observations to the IDH1/MGMT status, with a particular focus on the early onset population of young adults who develop primary glioblastoma." (PMID 23451042, 2013). "We therefore investigated whether the GNS signature is characteristic of IDH1 wild-type glioblastomas." (PMID 23046790, 2012). "It was also found that IDH1 mutant glioblastomas predominantly involved the frontal lobe." (PMID 22427879, 2012). "The IDH1 and IDH2 genes are mutated in glioblastoma and AML cancer patients." (PMID 22174824, 2011). "The latest 5th edition recently refined the diagnosis of glioblastoma by adopting a multi-layered integrated approach incorporating new molecular criteria such as TERT promoter mutation, EGFR amplification or chromosomal 7 + gain / chromosomal 10- loss for IDH-1 wildtype tumors." (PMID 40067514, 2025). "Using both commercially available GBM cell lines (U87 IDH1 WT and MUT) and glioblastoma organoid-derived patient cell lines, we evaluated the efficacy of the inhibitor candidates alone and in combination with TMZ." (PMID 41285884, 2025). "Similarly, it is possible that some cases classified as IDH-wild type (glioblastoma) should have been categorized as astrocytomas since only IDH-1 mutations were evaluated and IDH-2 mutations were not assessed." (PMID 39917141, 2025). "Adult-type diffuse gliomas are split into three groups: (i) grade 4 isocitrate dehydrogenase 1/2 wildtype (IDHwt) glioblastoma (GBM); (ii) grade 2–4 IDH1/2 mutant (IDHmut) astrocytoma; (iii) grade 2–3 IDH mutant (IDHmut) oligodendroglioma." (PMID 40075681, 2025).
glioblastoma (continued). "Specifically, the genomic difference between glioblastoma and IDH1/2-mutant astrocytoma (median JD: 0.147) was significantly higher than the genomic heterogeneity within glioblastoma (median JD: 0.088, P < .001) or IDH1/2-mutant astrocytoma (median JD: 0.059, P < .001)." (PMID 39164213, 2025). "Thus, the findings were consistent with a grade 4 IDH-1 wild-type glioblastoma." (PMID 39590169, 2024). "The most recent 2021 classification from the World Health Organization (WHO) divides these tumors into astrocytomas, oligodendrogliomas, and glioblastomas (GBMs) based on histologic features and the presence or absence of a somatic mutation in the IDH1/2 genes." (PMID 37958846, 2023). "Isocitrate dehydrogenase-1 [IDH1]-wild-type glioblastoma (GBM) is a highly aggressive and heterogeneous tumor with poor survival outcomes." (PMID 37434262, 2023). "IDH1/2 mutations are frequent in low-grade gliomas (LGG) and glioblastomas (GBM), which produce oncometabolite 2-HG and inhibit TET2 activity." (PMID 37550284, 2023). "Interestingly, glioblastomas with IDH1 mutation have low levels of MCT1 and MCT4 and present no changes in hyperpolarized [1-13C] lactate in MRSI." (PMID 38139462, 2023). "Glioblastoma (GBM), which is classified as Isocitrate dehydrogenase (IDH1) wild-type (IDH1wt) according to 2021 WHO, is the most common and aggressive form among primary malignant brain tumors." (PMID 37735434, 2023). "However, Cox regression analysis showed that IDH1 mutation status did not significantly impact survival in this cohort of glioblastoma." (PMID 35419292, 2022). "We build an ML model using radiomics features to predict mutations of the isocitrate dehydrogenase NADP+ 1 (IDH1) gene, which has been shown to be a marker of oncogenesis and is one of the most specific biomarkers in the diagnostic classification of secondary glioblastoma multiforme." (PMID 35890885, 2022). "Our data also strongly support that rare DNA 6mA rather than relatively abundant DNA 5-methylcytosine and 5-hydroxymethylcytosine is a hallmark of poor prognosis of IDH1/2 mutation-absent glioblastoma patients, reflecting the incidence of cytotoxic stresses and subsequent release of m6A nucleoside." (PMID 35501312, 2022). "Targeting IDH1 (isocitrate dehydrogenase 1) that is overexpressed in aggressive TETs using IDH1 Inhibitors such as GSK864 as reported in preclinical tests in glioblastomas could be a new therapeutic option, especially when used in combination with inhibitors of RTK-PI3K signaling." (PMID 35326714, 2022). "No IDH1 mutation was detected in primary glioblastomas, midline gliomas or pilocytic astrocytomas." (PMID 36289655, 2022). "Therefore, the histology is consistent with a grade 4 IDH-1 wild-type glioblastoma typically found in the elderly population, but her prognosis may be better than average due to the methylated promoter of MGMT." (PMID 36703629, 2022). "Glioblastoma multiforme (GBM) is the most common type of malignant brain tumor, among which IDH1-wild type GBM has a poor prognosis." (PMID 35571123, 2022). "Glioblastoma (GBM; grade-IV isocitrate dehydrogenase-1 [IDH1] wildtype glioma) is the most common locally invasive and aggressively infiltrative primary malignant brain tumor, making total resection implausible." (PMID 36239858, 2022). "Mutations in human cytosolic and mitochondrial NADP-IDH (IDH1 and IDH2, respectively) are frequently identified in a variety of human cancers, such as glioblastoma (GBM) and angioimmunoblastic T cell lymphoma (AITL)." (PMID 34291089, 2021). "Recently, tumor vaccines against IDH1 have been successful in slowing the progression of glioblastoma GBM." (PMID 34603319, 2021).
glioblastoma (continued). "Isocitrate dehydrogenase 1 (IDH1) mutations, which are associated with more favorable outcome, represent a new tumor group termed ‘adult-type, diffuse glioma, IDH-mutant, astrocytoma, grades 2-4’, while glioblastoma is now reserved to the ‘adult-type, diffuse glioma, IDH1 wildtype’." (PMID 34422657, 2021). "ATRX and IDH1 mutations appeared to be more commonly altered in glioblastoma that lack RTK genomic variations, genetically resembling to that of secondary GBM." (PMID 32794373, 2020). "Thus, these tumors showed characteristic copy number alterations observed for classical glioblastomas, which is further supported by the observation that none of these tumors had an IDH1 mutation." (PMID 32604718, 2020). "Moreover, the study found that the absence of isocitrate dehydrogenase 1 (IDH1) mutation in LGGs was similar to glioblastoma regarding molecular and clinical characteristics." (PMID 33363544, 2020). "IDH1 gene mutation could be identified in most of the patients with low‐grade (grade II–III) astrocytomas and glioblastomas, whereas the gene mutation was rarely detected in patients with primary glioblastomas." (PMID 32069381, 2020). "Similarly there was also no overt relationship between BCL6 level and IDH1 mutation, another mutation more common in secondary glioblastoma." (PMID 32320427, 2020). "It was observed that the expression of PDGF ligand correlates with poor prognosis factors such as age at GBM diagnosis, phosphatase and tensin homolog deletion (PTEN), and isocitrate dehydrogenase 1 (IDH1) mutation in glioblastoma patients." (PMID 32152825, 2020). "Regarding these results, we hypothesize that the MGMT-negative glioblastoma cell line U87 might serve as a model for highly aggressive, mHsp70-positive primary glioblastomas without IDH-1 mutation." (PMID 32276468, 2020). "In addition, silencing IDH1 in glioblastoma cells improved responses to radiotherapy." (PMID 31888244, 2019). "Furthermore, we also proved that ALDOC mRNA and protein expression inversely correlated with non-mutated IDH1 expressions in glioblastoma patient cohorts." (PMID 31450822, 2019). "Moreover, IDH1 has been recognized as a key prognostic factor for glioblastoma patients." (PMID 31450822, 2019). "However, the NAMPT levels in SVGp12-IDH1R132H were still below the NAMPT levels seen in the glioblastoma cells with and without IDH1 mutation." (PMID 31888244, 2019). "Recent studies suggest that glioblastomas (GBMs) contacting the subventricular zone (SVZ) as the main adult neurogenic niche confer a dismal prognosis but disregard the unique molecular and prognostic phenotype associated with isocitrate dehydrogenase 1 (IDH1) mutations." (PMID 30669568, 2019). "Additionally, the concordance of low ALDOC and high non-mutated IDH1 expressions predicted a stronger poor prognosis in glioblastoma patients compared to each of above tests presented alone." (PMID 31450822, 2019). "However, in a subset analysis, an IDH1 mutation was found in only 21 (6.1%) of 343 glioblastoma patients, and did not correlate to tumor contact with the SVZ." (PMID 31603915, 2019). "IDH1 activity is also an important factor in metabolic adaptation, which supports an aggressive growth of primary glioblastomas (GBM) maintained despite difficult metabolic conditions." (PMID 30857299, 2019). "Approximately 55–80% of secondary glioblastomas, those that progress from low-grade diffuse astrocytoma or anaplastic astrocytoma and occur in younger patients, have somatic mutations in the isocitrate dehydrogenase 1 (IDH1) gene, which are absent in primary glioblastoma in older patients." (PMID 29642503, 2018). "Isocitrate dehydrogenase 1 (IDH1) has been proven as a prognostic and predictive marker in glioblastoma (GBM) patients." (PMID 30426720, 2018).